INS (insulin)
Diseases named in the same sentence as INS in open-access papers (continued):
Sharing a sentence is not in itself a finding about the gene and the disease.
type 2 diabetes (continued). "The remaining two studies included subjects with type 2 diabetes without insulin therapy and with moderate hypercholesterolemia (mean values: 5.9 and 6.1 mmol/L, resp)." (PMID 27882320, 2016). "For this retrospective cohort study, people with type 2 diabetes who progressed to insulin with or without metformin from 2000 onwards were identified from the UK Clinical Practice Research Datalink (≈7% sample of the UK population)." (PMID 27152598, 2016). "Cinchonain Ib was found to enhance insulin secretion from INS-1 cells in the same study and may have insulinotropic effect for managing type 2 diabetes." (PMID 27929430, 2016). "For example, a survey of 2061 patients with type 2 diabetes who were not enrolled in insulin treatment found that they perceived the clinical efficacy of insulin as low and would blame themselves if they had to begin insulin therapy." (PMID 26743909, 2016). "Participants with type 2 diabetes, not using insulin, were followed until November 21, 2012 or death." (PMID 27537359, 2016). "Type 2 diabetes, accounting for 90%–95% of all the cases, is characterized by high blood sugar, insulin resistance, and relative lack of insulin." (PMID 28773977, 2016). "These patients were characterized by a 1.5-fold further increase in 18F-FDG uptake compared with type 2 diabetes patients not using insulin." (PMID 27887576, 2016). "The new drug for type 2 diabetes, the sodium-glucose cotransporter 2 (SGLT-2) inhibitor, is reversible inhibitor of SGLT-2, leading to reduction of renal glucose reabsorption and decrease of plasma glucose, in an insulin-independent manner." (PMID 26668677, 2016). "Despite this, fasting blood glucose did not change and, in line with data in healthy adults and obese women, the results demonstrated no impact of HIIT on central insulin sensitivity in adults with type 2 diabetes." (PMID 26350611, 2016). "T2DM was previously known as non-insulin-dependent DM (NIDDM) or adult-onset diabetes, which is an age-related metabolic disease resulting from insulin resistance of peripheral tissues and inadequate insulin-secreting pancreatic β cell function." (PMID 26907255, 2016). "Subsequently, we compared 18F-FDG uptake between PAD patients with type 2 diabetes with or without exogenous insulin in addition to oral antidiabetic drugs." (PMID 27887576, 2016). "In a previous study, soy leaf exhibited non-HDL-cholesterol lowering effects in hamsters —as well as ethyl acetate extracts of soybean leaves, including pterocarpan—ameliorated the insulin sensitivity and improved the plasma glucose levels in high-fat diet (HFD)-induced type 2 diabetic mice." (PMID 27869712, 2016). "GPR40 is expressed in both pancreatic beta cells and gut endocrine cells, suggesting that its agonism might enhance insulin and GLP-1 secretion in type 2 diabetes." (PMID 26661410, 2016). "Studies found that defects in insulin signaling were selective with a dramatic reduction of insulin-stimulated IRS-PI3K-Akt pathway rather than the MEK/ERK pathway in type 2 diabetic patients." (PMID 27274905, 2016). "Our finding of a smaller excess incidence of cancer among persons with type 1 diabetes than was previously observed in persons with type 2 diabetes does not support the notion that insulin therapies contribute to the observed elevated incidence." (PMID 26924393, 2016). "Self-monitoring of blood glucose among people with type 2 diabetes not treated with insulin does not appear to be effective in improving glycemic control." (PMID 27458809, 2016). "For type 2 diabetes, around 80% who are insulin-dependent and 50% who are non-insulin-dependent will have DR after 20 years." (PMID 26948311, 2016). "Type 2 diabetes (formerly called non-insulin-dependent or adult-onset) results from the body's ineffective use of insulin." (PMID 27478845, 2016). "Type 2 diabetes (T2D), however, often first appears in adults when the body becomes resistant to insulin or fails to make sufficient amounts of insulin." (PMID 27729921, 2016).
type 2 diabetes (continued). "This study indicates that exercise training can improve both conduit and microvascular endothelial function and health, independent of changes in insulin sensitivity in adolescents with type 2 diabetes." (PMID 26887327, 2016). "In the WESDR, higher serum total cholesterol was associated with a higher prevalence of retinal hard exudates in both younger- and the older-onset groups taking insulin but not in those with type 2 diabetes using oral hypoglycemic agents." (PMID 27275953, 2016). "It has been shown that treatment with recombinant human leptin does not improve insulin sensitivity in obese patients with type 2 diabetes, contrary to what happens in patients with severe leptin deficiency." (PMID 27216013, 2016). "Mice lacking the Ptp1b gene presented improved insulin sensitivity with increased tyrosine phosphorylation of IR and did not develop type II diabetes or obesity." (PMID 26989693, 2016). "A possible relation between eating patterns and response to GLP-1 RA has never been studied in patients with type 2 diabetes on insulin." (PMID 26597956, 2016). "To characterize GADAb-positive patients with adult-onset diabetes who do not require insulin therapy for >5 years (NIR-SPIDDM), we conducted a nationwide cross-sectional survey in Japan." (PMID 27177031, 2016). "C-peptide represents the residual insulin secretion, and it is not usually depleted in patients with type 2 diabetes." (PMID 27457238, 2016). "Type 2 diabetes patients feature a bihormonal disorder where either absolute insulin insufficiency or relative lack of insulin is present alongside fasting and postprandial hyperglucagonemia." (PMID 25961284, 2015). "There is no universal consensus for the optimal method of starting insulin therapy in patients with type 2 diabetes (T2DM) who do not respond to oral anti-diabetic drugs (OADs)." (PMID 25874190, 2015). "Due to its role in insulin secretion, the GLP-1 receptor has received significant attention as a possible therapeutic target for treating type 2 diabetes, resulting in the approval of three peptide analogues of GLP-1 (liraglutide, exenatide, and lixisenatide) for clinical use." (PMID 26198634, 2015). "Obesity is very common in type 2 diabetes where the adipocytes cells secret a number of biological proteins (leptin, TNF-alpha, resistin, and adiponectin) that modulate insulin secretion or action and may contribute to insulin resistance." (PMID 26273663, 2015). "However, considering that pancreatic islets from patients afflicted with type II diabetes are almost all converted into amyloids, this massive IAPP deposition most likely interferes with normal β-cell functions, such as insulin release." (PMID 26576436, 2015). "Together, our findings suggest that impaired insulin signaling and increased SOCS expression in the liver are impaired due to a lack of physical activity and represent early stages of metabolic dysfunction leading to type 2 diabetes." (PMID 25713323, 2015). "In individuals with type 2 diabetes, the first-phase insulin response is severely diminished or absent, resulting in persistently elevated postprandial glucose throughout most of the day12." (PMID 26607841, 2015). "The aim of the present study was to compare the effects of oral glutamine with whole protein low in glutamine on: (i) first- and second- phase insulin response using the gold standard hyperglycemic glucose clamp; and (ii) total and active GLP-1 in well-controlled type 2 diabetes patients." (PMID 25811109, 2015). "Associations of lymphocyte subpopulations with fasting glucose, HbA1c, and insulin among participants without type 2 diabetes." (PMID 26458065, 2015). "TIMP-1 may represent a novel pharmacological target for improving hepatic insulin sensitivity in patients with the metabolic syndrome, NASH and Type 2 diabetes." (PMID 26168159, 2015).
type 2 diabetes (continued). "Surgical treatment consisting ofduodenojejunal bypass with or without ileal segment interposition has been shown topermit clinical control of patients with type 2 diabetes without the need for insulin ororal hypoglycemic agents." (PMID 26734798, 2015). "Given the importance of insulin clearance in type 2 diabetes and the role of IDE in its regulation, it is not surprising that alterations in the expression and the activity of IDE are closely related to the onset and development of type 2 diabetes." (PMID 25822220, 2015). "In this 48-week, open-label, randomized, multi-center, crossover phase IV trial, insulin naïve type 2 diabetes patients with blood glucose not at target on oral hypoglycemic agents had basal insulin added to their treatment regimen." (PMID 26055391, 2015). "Hypoglycemia is a common side effect of insulin therapy in type 2 diabetes, and has a negative impact on mortality, morbidity and quality of life." (PMID 25698911, 2015). "The most common form is type 2 diabetes (T2D) which is characterized by the lack of proper response to insulin in the peripheral tissues, a phenomenon known as the insulin resistance." (PMID 25716801, 2015). "Linagliptin lowered serum levels of oxLDL in patients with type 2 diabetes who did not switch from insulin treatment and who were undergoing HD." (PMID 25995772, 2015). "Insulin-stimulated glucose uptake was abolished in myotubes from type 2 diabetics compared to cells from non-diabetics (p = 0.01), implying a conserved insulin resistance in cultured cells." (PMID 25790476, 2015). "Non-severe hypoglycaemic events are common in Type-1 and insulin-treated Type-2 diabetes patients in Austria." (PMID 25421366, 2015). "The pathogenesis of type 2 diabetes in non-obese Asian Indians [body mass index (BMI) < 25 kg/m2] is ill-understood and the relative contributions of insulin secretion and insulin resistance continue to be debated." (PMID 26474415, 2015). "Contrary to type 2 diabetes, type 1 diabetes is an autoimmune disorder leading to decreased insulin release until there is a complete lack of insulin as a result of the destruction of the insulin-producing cells." (PMID 25733033, 2015). "A high dose of barley β-glucan supplement (6.31 g β-glucan) improved the glucose and insulin responses when added to a high-carbohydrate food in lean, healthy men without type 2 diabetes." (PMID 26690472, 2015). "In this respect, our data suggests that sustained high levels of glucagon, usually seen in type 2 diabetes, may lead to a decline in hepatic GSH levels that decrease postprandial insulin sensitivity, culminating in a state of insulin resistance." (PMID 25961284, 2015). "Alzheimer’s disease patients also have impaired glucose regulation but the dysregulation is not as severe as in type 2 diabetes, since glucose homeostasis is a result of both insulin resistance and insulin secretion." (PMID 25755673, 2015). "In another study that identified a polymorphism involved in the onset and progression of type 2 diabetes, the KCNJ15 polymorphism was observed in many non-overweight diabetic patients of Japan, whose ability to secrete insulin tended to decrease over time." (PMID 26215867, 2015). "Of the 88 patients with type 2 diabetes, 56 were treated by diet and exercise without any pharmacotherapy, 17 received metformin, 20 were treated with insulin (with or without metformin), one received glimepiride and one pioglitazone." (PMID 25596852, 2015). "Among those diabetics, 5 had type 1 (all of them were insulin dependent) and 15 had type 2 diabetes (all of them were not insulin dependent)." (PMID 25642344, 2015). "Type 2 diabetes mellitus (T2DM) is a common heterogeneous and complex disease that is characterized by hyperglycemia resulting from impaired pancreatic β-cell function and a decreased action of insulin on target tissues." (PMID 26329304, 2015).
type 2 diabetes (continued). "Maintaining a normal blood glucose level in type 2 diabetics by use of either oral medications or insulin will only fulfill the guideline requirements and will not achieve any long term benefits." (PMID 26521236, 2015). "Eligible patients are age ≥18, have type 2 diabetes, and have used insulin for ≥3 months with/without other antidiabetic medications." (PMID 26353820, 2015). "Proinflammatory cytokines, such as tumor necrosis factor alpha (TNF-α) and IL-6, generated during the innate response, can inhibit insulin signaling through the phosphorylation of insulin receptor substrate 1 (IRS-1), serving to link inflammation with IR and type 2 diabetes." (PMID 26458065, 2015). "However, in patients with type 2 diabetes, plasma levels of glucagon remain abnormally high after ingestion of a meal and may contribute to impaired glucose tolerance further suggesting that the cAMP signaling pathway is upregulated in insulin-resistant individuals." (PMID 25961284, 2015). "This current study expands those findings by first characterizing the fasting blood glucose, insulin, total cholesterol, HDL cholesterol, LDL cholesterol, and triglyceride values in Mexican-Americans with type 2 diabetes using samples from our En Balance study." (PMID 26703680, 2015). "Since the incretin hormones, glucagon-like peptide-1 and glucose-dependent insulinotropic polypeptide (GIP), are major regulators of post-prandial insulin secretion, inhibition of DPP4 by the gliptin family of drugs has gained considerable interest for the therapy of type 2 diabetic patients." (PMID 26284071, 2015). "In obese men with type 2 diabetes, BMI, HOMA-IR, and fasting insulin as well as fasting glucose levels were even higher as compared to obese men without type 2 diabetes." (PMID 25771885, 2015). "Additionally, taking into account that disturbances in biochemical parameters (insulin, glucose, and lipoproteins) bring about health deteriorations, it could be tentatively postulated that ABSI may be of importance in risk prognosis of type 2 diabetes and/or atherogenesis." (PMID 25890016, 2015). "Metformin is an effective treatment option for women with type 2 diabetes in pregnancy with or without add-on insulin who require pharmacological treatment for glycemic control in our resource poor setting." (PMID 25874236, 2015). "In patients with type 2 diabetes, the number of LDL B/E cell-surface receptors is significantly reduced, which may be due to reduced insulin-mediated expression and could be responsible for observed impairments in LDL catabolism." (PMID 25725623, 2015). "The effect of the periodicity of the pulses in the hepatocytes is not well known, but non-pulsatile insulin secretion is a well-known early indicator of type 2 diabetes, indicating a predominant role in the maintenance of biological functions." (PMID 26222615, 2015). "The inclusion criteria for the participants were: people with type 2 diabetes; blood sugar was not well controlled despite taking maximum oral glucose-lowering drugs; and insulin-naive." (PMID 25341370, 2014). "Protein tyrosine phosphatase (PTP) 1B, a negative regulator of the insulin and leptin signaling pathways, is currently considered a promising target for the development of novel therapeutic approaches used to treat insulin-resistant type 2 diabetes mellitus (IR-T2DM)." (PMID 24555682, 2014). "Insulin secretion in Japanese individuals is reported to be less than half that of whites, and most Japanese patients with type 2 diabetes do not have IR." (PMID 25166121, 2014). "The diabetic participants did not receive antihyperglycemic medication or insulin therapy, and no participants with impaired fasting glucose or impaired glucose tolerance were newly diagnosed with type 2 diabetes during the study." (PMID 25015735, 2014).
type 2 diabetes (continued). "Several frog peptides that were first identified on the basis of their abilities to inhibit growth of bacteria have been shown to stimulate release of insulin from BRIN-BD11clonal β-cells and improve glucose tolerance in mice and so show potential for treatment of patients with Type 2 diabetes." (PMID 24434793, 2014). "In conclusion, our findings suggest that nutritional supplementation of db/db mice with selenate does not improve or prevent the symptoms of type 2 diabetes, although hyperglycemia was decreased as a result of increasing insulin production and secretion." (PMID 24983750, 2014). "Studying the work involved in insulin initiation for people with type 2 diabetes (T2D) provides a lens for exploring the factors that may influence how effectively generalist and specialist health professionals across both primary and secondary care work together to improve health outcomes." (PMID 24479762, 2014). "Approximately 200 adults aged 50 to 75 years with type 2 diabetes, treated with either diet alone or oral hypoglycaemic agents (not insulin), will be recruited." (PMID 25376884, 2014). "Potential roles of apoA-I/HDL functionality in the aetiology of type 2 diabetes with multiple targets for apoA-I/HDL in glucose homeostasis have recently been suggested, including improved insulin secretion and increased glucose uptake in skeletal muscle and adipocytes." (PMID 24442447, 2014). "Following a diagnosis of coma due to diabetic ketoacidosis (DKA), acute renal failure, acute pancreatitis, and sepsis, insulin therapy (regular insulin, 7 U/h) and antimicrobial therapy (meropenem trihydrate) were initiated in conjunction with adequate hydration." (PMID 25184062, 2014). "Later, when pancreatic insulin secretion is less able or can no longer compensate for impairments in glucose homeostasis, Akt activation diminishes even further and type 2 diabetes worsens." (PMID 26237474, 2014). "Patients studied by Sigal had type 2 diabetes of at least 6 months of duration, mean HbA1c was between 6.6 and 9.9% but none of the participants were treated with insulin." (PMID 25423489, 2014). "In type 2 diabetes, either the body does not produce enough insulin or the cells ignore the insulin necessary for the use of glucose as an energy supply." (PMID 24991532, 2014). "Increased hepatic glucose production, or impaired insulin suppression of it, is one of the two pathways (endogenous glucose production and glucose disposal) that are responsible for hyperglycemia, and thus NAFLD promotes type 2 diabetes." (PMID 25411646, 2014). "Unlike type 1 diabetes, insulin injections are not initially required for type 2 diabetes treatment, for the early stage of type 2 diabetes is characterized by insulin overproduction." (PMID 25202328, 2014). "Our current findings support the contention that the rapid-acting insulin analog insulin lispro is as effective in achieving glycemic control in geriatric patients as it is in non-geriatric patients with type 2 diabetes at a similar dose." (PMID 23959960, 2014). "Type 2 diabetes, also known non-insulin-dependent diabetes, is the most prevalent type of the disease and involves defects in the secretion and action of insulin." (PMID 24716713, 2014). "Insulin sensitizing drugs such as pioglitazone are not uniformly treatment effective among individual type 2 diabetic patients." (PMID 25405601, 2014). "In both men and women, at the time of diagnosis of type 2 diabetes, fasting IGFBP-1 may rise in relation to insulin, which may be in part due to hepatic insulin resistance." (PMID 26237614, 2014). "Indexes of insulin sensitivity (Matsuda index) and early insulin responses to oral glucose (INS) that were derived from baseline and follow-up OGTTs did not appear to be significant predictors for the development of type 2 diabetes." (PMID 24498035, 2014).